SNORD60 (small nucleolar RNA, C/D box 60)
Synonyms: U60; RNU60
Gene: Small nucleolar RNA gene on chromosome 16 (2,155,023 to 2,155,105, reverse strand). Ensembl gene ENSG00000206630.
Gene Ontology:
Biological process: RNA processing
Cellular component: nucleolus
Homologues: Orthologues: macaque SNORD60 (98% identical), pig SNORD60 (95% identical), mouse Snord60 (80% identical), rat Snord60 (80% identical).
Diseases named in the same sentence as SNORD60 in open-access papers:
SNORD60 is named in the same sentence as 6 diseases in open-access papers, as found by Europe PMC text mining. Sharing a sentence is not in itself a finding about the gene and the disease. The quoted sentences say what the papers report.
lymph node metastases (1 paper, 2022). "Increased SNORD60 expression was linked with lymph node metastases and the TNM stage (P < 0.05)." (PMID 35711521, 2022). "The association between SNORD60 expression and clinicopathological characteristics, including sex, age, TNM stage, pathological T category, lymph node metastasis, and distant metastasis, was investigated." (PMID 35711521, 2022).
renal cell carcinoma (1 paper, 2024). "We also revealed a three-snoRNA signature: SNORD15A, SNORD35B, and SNORD60 were upregulated in the tissues and urinary sediment of renal cell carcinoma (RCC), serving as novel potential biomarkers for RCC diagnosis." (PMID 38311725, 2024).
cancer (3 papers, 2022 to 2023). A tumor composed of atypical neoplastic, often pleomorphic cells that invade other tissues. "SNORD60, also known as U60/rNU60, is encoded by an 83 bp genome on chromosome 16p13.3, the most commonly amplified chromosomal regions which may have an oncogenic role in developing different cancers." (PMID 35711521, 2022). "Additionally, the higher expression of SNORD60, a novel candidate for cancer prognosis, clearly correlated with poorer OS in the RT-treated cases." (PMID 36585466, 2022).
SNORD60 also shares sentences with these, for which no sentence is quoted: endometrial cancer (1 paper); myelodysplastic syndrome (1); tumor (1).